IL1B (interleukin 1 beta)
Diseases named in the same sentence as IL1B in open-access papers (continued):
Sharing a sentence is not in itself a finding about the gene and the disease.
Stroke (continued). "In previous studies, high systemic levels of the proinflammatory cytokine IL-1β have been associated with cytokine-induced sickness behavior after experimental stroke." (PMID 37212886, 2023). "The excessive secretion of IL-1β by microglia was shown to cause neuronal death in rat models of stroke and PD." (PMID 34216357, 2022). "The NLR family, which includes NLRP3, IL-1β, and Caspase-1, has been reported to play critical roles in rodent models of the ischemic brain injury, and stroke is linked to a single-nucleotide polymorphism of IL-1β." (PMID 35497095, 2022). "While IRF5 CKO led to a decrease only in IL-1β expression after stroke, IRF4 CKO caused up-regulation of both IL-1β and TNF-α in ischemic microglia." (PMID 35963621, 2022). "ISG15 is robustly induced by IFNs, interleukin 1 beta (IL-1β), pathogenic infection, lipopolysaccharides (LPS), retinoic acid (RA), hypoxia, experimental stroke traumatic brain injury, or DNA-damaging stresses." (PMID 36319753, 2022). "IL1β has been strongly associated with cancers and one IL-1β haplotype has been linked to the risk of stroke in small vessels." (PMID 35432334, 2022). "Inflammatory cytokines (TNF-α and IL-1β) and adhesion cell molecules are useful to evaluate the risk of stroke and have fundamental roles in the pathophysiology of brain ischemia." (PMID 35126096, 2021). "The M1-type macrophage secretes pro-inflammatory factors, such as reactive oxygen species (ROS), tumor necrosis factor-alpha (TNF-α), and interleukin 1 beta (IL-1β), which are well documented to damage the AS plaque stability and cause stroke." (PMID 34820428, 2021). "Polymorphisms in IL-1β gene are associated with both apical periodontitis and the risk of myocardial infarction or stroke." (PMID 32388515, 2020). "Studies have reported a positive association between tumor necrosis factor alpha (TNF-α) and IL-1β with ischemic stroke risk or future stroke recurrence." (PMID 33153204, 2020). "Overall, IL‐1β blockade is associated with a reduction in non‐fatal and fatal myocardial infarction, stroke, hospitalisation for unstable angina and, ultimately, a reduction CV death." (PMID 33204425, 2020). "An IL-1β haplotype in postmenopausal women and hypertensive persons, and an IL-1α haplotype in Koreans are associated with increased stroke risk." (PMID 32503645, 2020). "In the present study, we present supporting evidence for a role of the IL1B inflammatory gene in stroke susceptibility." (PMID 31480765, 2019). "The relative protein expression levels of TNF-α and IL-1β were significantly lower in CD200R1-deficient monocytes after stroke compared to WT controls (p ≤ 0.01 and p ≤ 0.05, respectively)." (PMID 30777093, 2019). "The pathogenic role of IL-1β in rodent models of stroke is well established; exogenous administration of IL-1β increased brain oedema, while IL-1α/β double-knockout mice showed ameliorated infarct size." (PMID 31281252, 2019). "The relationship of IL1B polymorphism and stroke has been examined in several previous studies and our results remain in line with those presented so far." (PMID 31480765, 2019). "Our findings confirm previous genetic observations, highlighting the need for further functional studies, particularly in view of the possible utility of IL1B as a diagnostic biomarker for stroke." (PMID 31480765, 2019). "For the IL1B:C(-31)T polymorphism, we found that carriers of the C allele were associated with a higher risk of overall stroke." (PMID 31480765, 2019). "In both a murine model of stroke and in patients, increased IL-1β levels were observed after stroke, and hypothermia treatment was associated with lower IL-1β levels." (PMID 31644666, 2019). "These pro-inflammatory cytokines (IL-1β and IL-1α) are involved in the underlying mechanism of various chronic inflammatory CNS conditions, such as stroke, Alzheimer’s disease, Parkinson’s disease, and epilepsy." (PMID 29334965, 2018).
Stroke (continued). "In probing the effects of circulating pro-inflammatory cytokines on BBB permeability, a study found that IL-1β contributes significantly to the loss of BBB integrity following stroke." (PMID 29786644, 2018). "Mice in which both IL-1α and IL-1β have been deleted (IL-1α/β double KO) have markedly reduced damage in response to experimental stroke caused by middle cerebral artery occlusion (MCAo)." (PMID 22206506, 2011). "IL-1β is strongly associated with PSD at 6 months after stroke." (PMID 40529498, 2025). "Additionally, the presence of the -511 T allele has been associated with higher IL-1β levels shortly after a stroke, indicating a potential link to PSD, although this association appears to diminish over time." (PMID 38377025, 2024). "Additionally, our study also revealed that elevated ASC and IL-1β levels were associated with an increased risk of recurrent stroke." (PMID 39737165, 2024). "Moreover, in a 1-year follow-up assessment of blood biomarkers in patients who experienced stroke (64.5 ± 9.5 years), higher TNF-α and IL-1β levels were associated with poor outcomes at 1-year post-stroke." (PMID 37728582, 2024). "Furthermore, high level of ASC, IL-1β at baseline were risk factors of recurrent stroke (P=0.034, HR (95%CI): 3.33 (1.096,10.161), and P=0.037, HR (95%CI): 7.67 (1.126,52.31), respectively)." (PMID 39737165, 2024). "Therefore, we aim to determine the role of interleukin-1 beta in atherosclerotic lesions of the internal carotid artery as a risk factor for stroke and the role of this biomarker in stroke prognosis." (PMID 37893508, 2023). "IL-1β is a pro-inflammatory cytokine with neurotoxic effects although other inflammatory factors may cause stroke." (PMID 38089678, 2023). "In the early phase of stroke, astrocytes can produce excess inflammatory cytokines, such as IL-1β or release glutamate and MMP-2 that causes degradation of matrix protein and subsequent blood-brain barrier (BBB) disruption, which eventually damages neuronal viability and causes encephaledema." (PMID 37199575, 2023). "On the other hand, we cannot exclude the possibility that this CRP elevation was associated directly to stroke and the release of IL-1β both in the brain and in the systemic circulation, inducing a cascade of sympathetic system activation catecholamine release in the extracellular myocardium." (PMID 37119383, 2023). "In contrast, the IL1B rs16944 has also been previously reported in association with lower risk of both MI and stroke in patients with early disease onset, indicating the increased risk of death observed in this study may represent non-CHD related death." (PMID 35994463, 2022). "The profound effects of the IL-1β antibody on neuropathology during chronic hypoperfusion is similar to the magnitude of effects that we have observed with blood replacement following acute hypoperfusion cause by stroke in mice." (PMID 33918659, 2021). "IL-1β has been associated with stroke in SCA, and it has been suggested that IL-6 could be related to the development of pulmonary hypertension in SCA children." (PMID 33250889, 2020). "The cytokine interleukin-1β (IL-1β) has very strong pro-inflammatory effects on a variety of cell types and is implicated in the pathogenesis of numerous inflammatory diseases, including stroke, diabetes, and genetic auto-inflammatory disorder." (PMID 31174550, 2019). "Recently, IL-1β blocking therapy was demonstrated to decrease the risk for stroke in coronary artery disease patients with inflammatory atherosclerosis, while its modulatory role in cancer, macular degeneration and neurodegenerative disorders is also intensively investigated." (PMID 30721409, 2019). "In stroke patients the release of proinflammatory cytokine IL-1β is associated with poor outcome." (PMID 31544811, 2019).
Stroke (continued). "Further testing is required to determine the validity of the shown association between the mutant IL-1β genotypes TT, CT and the occurrence of other complications (leg ulcer, priapism, acute chest syndrome, splenic sequestration, retinopathy and stroke) in SCD patients." (PMID 31205626, 2019). "Therefore, interventional studies aiming to block microglia/macrophages M1 polarization, or directly target IL-6 and IL-1β, will be needed to evaluate if a causal link exists between inflammation and stroke severity in CKD." (PMID 31015533, 2019). "Moreover, IL-1β plays a crucial role in the exacerbation of acute neurodegeneration caused by ischemia, head trauma and stroke." (PMID 27586269, 2016). "This might have provided some mechanistic insights into the relationship between variants of the IL-1α and IL-1β genes and IS according to stroke etiology." (PMID 24063019, 2013). "The most extensively studied cytokines associated with stroke are IL-1β, IL-10, IL-6 and TNF-α." (PMID 23514014, 2013). "IL-1β has been associated with brain oedema formation after stroke." (PMID 22114895, 2011). "However, astrocyte activation also has detrimental effects: increased levels of interleukin-1β (IL-1β) may be linked to post-stroke cognitive impairment." (PMID 41450734, 2025). "The mechanism underlying rosuvastatin’s efficacy in stroke may be related to its ability to modulate microglial activation status, upregulate anti-inflammatory cytokines (IL-10) and suppress pro-inflammatory gene expression (IL-1β, TNF-α)." (PMID 32168831, 2020). "Our study suggests that inflammation, especially IL-1β signal, might be a risk for stroke onset." (PMID 23326018, 2012). "Therefore, patients with multiple risk factors for heart disease or stroke might benefit from neutralization of systemic IL-1β activity." (PMID 23130147, 2012). "IL-1β, another key pro-inflammatory molecule, is vital for immune responses, particularly within the central nervous system (CNS) following a stroke." (PMID 41598337, 2026). "When injected into the brain, both stroke-derived and inflammation-derived EVs induced pro-inflammatory cytokine gene expression (IL-1β and CXCL1), suggesting a potential role in neuroinflammation." (PMID 41751898, 2026). "Clinically, elevated plasma IL-1β levels within the first 24 h after stroke correlate with stroke severity, larger infarct volumes, and poorer neurological outcomes." (PMID 40869247, 2025). "We detected a decrease in α-defensin levels in the colon of mice receiving TFIF only after stroke, and these mice presented significantly increased levels of IL-1β and LPS in the colonic villous homogenate." (PMID 40026365, 2025). "Remarkably, in clinical studies, NLRP3 inflammasome components and IL-1β and IL-18 were found to be upregulated in postmortem brain tissue samples from patients with stroke." (PMID 40343197, 2025). "The colonic IL-1β levels in the mice showed that stroke alone or TFIF alone was sufficient to increase the levels of IL-1β in the gut, while the mice that underwent stroke combined with TFIF surgery presented the highest levels of IL-1β." (PMID 40026365, 2025). "In a stroke model, it improved neurological outcomes by reducing microglial activation and the expression of IL-6, IL-1β, and TNF-α, likely through inhibition of NF-κB." (PMID 40430456, 2025). "Key cytokines such as IL-6, IL-1β, TNF-α, and chemokines like IL-8 are rapidly released after stroke onset and are strongly associated with infarct size, neurological deterioration, and poor functional recovery." (PMID 40869247, 2025). "Our findings support the concept that lipid metabolism and specific FFA species contribute to post-stroke inflammatory tone and recovery biology, and they underscore IL-1β/IL-1Ra as potential mediators linking lipid perturbations with tissue inflammation." (PMID 41301455, 2025).
Stroke (continued). "Gene expression profiling revealed an upregulation of proinflammatory cytokines (TNF-α, IL-1β, IL-6) and the anti-inflammatory cytokine IL-10, particularly during the first three days post-stroke." (PMID 41373607, 2025). "Meanwhile, in stroke animals, this compound significantly decreased the circulating IL1-β, TNF-α and IFN-γ levels." (PMID 39859444, 2025). "In IS rat models, levels of proinflammatory cytokines TNF-α and IL-1β rise 1 h after a stroke starts." (PMID 40362186, 2025). "Clinically, elevated serum levels of interleukin-1β (IL-1β), interleukin-6 (IL-6), and tumor necrosis factor-α (TNF-α) at hospital admission correlate with significantly higher PSD risk in stroke patients." (PMID 41164411, 2025). "After a stroke, RNA sequencing showed an increase in genes associated with the TREM-1 and NLRP3 pathways, including Nfkb2 and IL-1β, which contribute to the neuroinflammatory response immediately after ischemia." (PMID 40867169, 2025). "The current investigation indicated that the genetic variation IL-1β-511T/C rs16944 was connected to stroke hazards." (PMID 40369205, 2025). "This aligns with research showing that inhibiting the thalamic NLRP3 inflammasome reduces IL‐18 and IL‐1β, leading to behavioral alleviation of thermal and mechanical pain sensitivity in a central post-stroke pain mouse model." (PMID 40329125, 2025). "Gene expression profiling showed upregulation of proinflammatory mediators (TNF-α, IL-1β, IL-6) and the anti-inflammatory cytokine IL-10, most prominently during the first three days post-stroke, with expression levels generally higher in older patients." (PMID 41373607, 2025). "Proinflammatory intracellular signaling cascades and transcription factors, for example, NF-κB, ROS, MMPs, and the release of proinflammatory cytokines, especially IL-1β, IL-6, and TNF-α, are associated with BBB dysfunction after stroke." (PMID 40740844, 2025). "We determined the elevated gene expression of pro-inflammatory cytokines such as IL1α and IL1β and TNFα as soon as 6 h after stroke induction." (PMID 40332314, 2025). "Stroke can trigger the release of various immune mediators, including IL-1β, TNF-α, calcitonin gene-related peptides, neuropeptides, and vasoactive intestinal peptides." (PMID 40098935, 2025). "Our previous study demonstrated that HDAC1 inhibition at 24 h after stroke exacerbated gliosis and elevated IL-1β and TNF-α, underscoring its importance in the acute phase." (PMID 41388741, 2025). "Elevated levels of pro-inflammatory cytokines—particularly IL-1β and IL-6—have been detected up to three months post-stroke, with higher concentrations observed in patients who experienced larger strokes." (PMID 41003011, 2025). "IL-1β and TNF-α breach the BBB and cause neuronal cell death in stroke, while IL-6 and IL-8 enhance oxidative stress and secondary damage in TBI." (PMID 39861166, 2025). "This study aimed to determine the potential interplay between FFAs, IL-1β, and IL-1Ra in stroke patients." (PMID 41301455, 2025). "Neutrophils synthesize and secrete pro-inflammatory factors such as TNF-α, IL-1β, and IL-6 and promote the expression of MMP9, which aggravates cerebrovascular endothelial cell injury after stroke and increases the risk of hemorrhagic complications." (PMID 38740617, 2025). "IL-1β has been detected within 1 h after ischemic brain injury, and IL-6 was increased within a few hours after onset of ischemia and up to 90 days after stroke." (PMID 40362186, 2025). "IL-1Ra counterbalances IL-1β as a potent anti-inflammatory protein and is synthesized after stroke to promote pro-resolving activity and limit ischemia-induced damage." (PMID 41009650, 2025). "Its ability to lower harmful mediators like IL-1β and IL-6 while enhancing protective factors such as IL-10 suggests a promising therapeutic strategy in stroke, traumatic brain injury, and subarachnoid hemorrhage." (PMID 40362194, 2025).
Stroke (continued). "In the early phase of stroke, IL-6 is induced by IL-1β and TNF-α and amplifies the inflammatory cascade." (PMID 40869247, 2025). "Pro-inflammatory cytokines like IL-1β, IL-2, and IL-6 are typically found at low levels in the brain, but their levels increase following a stroke." (PMID 40292265, 2025). "TNF-α and IL-1β, as the initiating substances in the inflammatory response chain, are involved in the whole process of stroke and can trigger an inflammatory cascade." (PMID 41471340, 2025). "The activity of protectin DX, 17 HDHA, and leukotriene B4 is correlated with IL-1β and IL-1Ra levels in the early subacute phase of stroke." (PMID 41009650, 2025). "In the GluN3A KO brain three days after stroke, inflammatory factors IL-1β, IL-6, IL-10, and/or TNFα were significantly elevated, while MEM largely prevented these increases." (PMID 41369361, 2025). "In patients in the early subacute phase of stroke, we observed an inverse correlation between C24:0 lignoceric acid and IL-1β and a positive correlation with IL-1Ra." (PMID 41301455, 2025). "In stroke, IL-10 modulates the immune response by inhibiting the synthesis of pro-inflammatory cytokines (e.g., IL-1β, IL-6, TNF-α), suppressing antigen presentation, and downregulating adhesion molecules on endothelial cells." (PMID 40869247, 2025). "The aim of this study was to analyze potential associations between eicosanoids and key inflammatory molecules, including IL-1β and its antagonist IL-1Ra, in the early subacute phase of stroke." (PMID 41009650, 2025). "Stroke induces the release of pro-inflammatory cytokines, such as interleukin-6 (IL-6), interleukin-1β (IL-1β), tumor necrosis factor-α (TNF-α), and interleukin-18 (IL-18), while reducing anti-inflammatory cytokines like IL-10 and IL-13." (PMID 40529498, 2025). "Although limited literature has documented the associations between IL-13RA2 and stroke, it is generally understood that IL-13RA2 can be upregulated by pro-inflammatory factors such as TNF-α and IL-1β." (PMID 40474979, 2025). "Emerging research implicates neuroinflammatory pathways in the pathogenesis of PSD, where post-stroke immune activation mediates elevated cerebral cytokine production (IL-1β, IL-6, TNF-α)." (PMID 41164411, 2025). "Single-cell assay for transposase-accessible chromatin with sequencing (ATAC-seq) of the BM revealed IL-1β, known to be elevated systemically after stroke, to be a key driver of epigenetic reprogramming in HSPCs post-stroke." (PMID 39256247, 2025). "Anakinra, an IL-1β antagonist, has shown neuroprotective effects in preclinical stroke and traumatic brain damage studies." (PMID 39861166, 2025). "The significant associations with IL-1β in our findings are noteworthy due to its established role as an inflammatory mediator in atherosclerotic cardiovascular disease (ASCVD), including stroke and CVD." (PMID 41255994, 2025). "IL-1β has been shown to worsen post-stroke inflammation and blood–brain barrier dysfunction, facilitating neuronal apoptosis." (PMID 40362194, 2025). "There is marked evidence in the literature supporting that IL-1β is a crucial inflammatory mediator in neuronal injury of stroke and TBI." (PMID 39540961, 2024). "TNF-α, IL-6, IL-1β, and IL-10 were also measured in peripheral blood samples to examine the possible effect of peripheral inflammatory response on the recurrent stroke." (PMID 38216560, 2024). "We examined the post-stroke inflammatory response in our model and found that the levels of pro-inflammatory cytokines, including interleukin (IL)-1β and IL-6, were significantly increased in the infarcted brain tissues." (PMID 39631782, 2024). "Elevated levels of IL-1β, IL-6, and TNF-α are closely associated with stroke occurrence, while some lipid-lowering drugs, such as statins, have been shown to reduce stroke risk through their anti-inflammatory effects." (PMID 38659020, 2024).